EZH2 (enhancer of zeste 2 polycomb repressive complex 2 subunit)
Diseases named in the same sentence as EZH2 in open-access papers (continued):
Sharing a sentence is not in itself a finding about the gene and the disease.
hematological malignancies (66 papers, 2011 to 2026). "Enhancer of zeste homolog 2 (EZH2) catalyzes H3K27me3, an epigenetic modification linked to gene silencing, and its overexpression contributes to the progression of hematological malignancies." (PMID 40308579, 2025). "EZH2 is overexpressed in both solid and hematologic malignancies and its overexpression is associated with a poor prognosis, making EZH2 a desirable therapeutic target." (PMID 39901520, 2025). "EZH2 is implicated in various hematologic malignancies, with literature suggesting its relevance in proposing novel therapeutic directions for AA." (PMID 38544839, 2024). "Currently, EZH2 inhibitors are being tested in a number of clinical trials and have been shown to benefit patients with certain hematological malignancies harboring activating mutations in EZH2." (PMID 37210576, 2023). "Heterozygous mutations of EZH2, particularly in its catalytic domain, are commonly found in hematologic malignancies." (PMID 37511137, 2023). "Mutations in EZH2 have been described in patients with various hematologic malignancies, including approximately 3% of PV." (PMID 35456443, 2022). "While dysregulation of EZH2 activity in hematological malignancies is predominantly caused by activating mutations, abundance of the methyltransferase in solid cancers including PDAC is mainly linked to overexpression." (PMID 34943970, 2021). "Both loss-of-function and gain-of-function mutations in EZH2 are found in hematological malignancies." (PMID 33374737, 2020). "In this model, several genes associated with HSC maintenance are regulated by EZH2, including the transcriptional regulators Evi-1 and Ntrk3 that are aberrantly expressed in hematological malignancies." (PMID 26497210, 2016). "More studies are required to clarify the role of EZH2 mutations in the therapy of hematologic malignancies." (PMID 25313314, 2014). "Additionally, EZH2 inhibition can affect hematopoietic and muscle stem cells, causing issues like blood disorder and impaired muscle repair." (PMID 38994197, 2024). "In particular, the evaluation of ezh2 expression and/or mutational status in several hematological malignancies may predict the efficacy of EZH2 inhibitors under development, as well as tazemetostat." (PMID 31921674, 2019). "Consistent with DepMap findings, EZH2 is found to play a crucial role in hematological malignancies." (PMID 41523653, 2026). "GSK126 (GSK2816126) is a highly selective and potent SAM competitive inhibitor of EZH2 and one of the first small-molecule inhibitors of EZH2 to enter clinical trials in hematologic malignancies and solid tumors." (PMID 41601922, 2026). "Here, we show that genetic inactivation of Asxl1 and Ezh2 in murine hematopoietic stem/progenitor cells results in highly penetrant hematological malignancies as observed in corresponding human diseases." (PMID 40561338, 2025). "The objective is to enhance the understanding of the relationship between EZH2 and AML among scholars and clinical researchers in the field of hematological malignancies, while exploring the potential of EZH2 as a molecular target." (PMID 39655332, 2024). "Many studies have shown that EZH2 overexpression is correlated with human hematological malignancies, and EZH2 has been established as a critical target for hematological cancers." (PMID 38346162, 2024). "EZH2 inhibitors (EZH2is) have been shown to be effective in treating hematologic malignancies, while their effectiveness in solid tumors remains limited." (PMID 38911968, 2024). "As far as EZH2 is concerned, its role in hematological malignancies is similarly complex and appears to be environment-dependent." (PMID 39655332, 2024). "For example, the combination of histone deacetylase (HDAC) inhibitors and Enhancer of Zeste Homologue 2 (EZH2) inhibitors has shown promise in hematological malignancies." (PMID 39275127, 2024).
hematological malignancies (continued). "The drugs targeting mutant PcG proteins such as EZH2 have been extensively investigated, and several of them have been applied to preclinical research of hematological malignancy treatment." (PMID 36566204, 2022). "For example, in hematologic malignancies, a gene mutation in the SF SRSF2, which regulates the AS of the EZH2 pre-mRNA, triggers a reduction in EZH2 isoform expression." (PMID 33407694, 2021). "Other cases of mutations in epigenetic factors that alter PPI, playing an important role in pathogenesis of hematologic malignancies, are mutations in the SET domain of EZH2." (PMID 33395407, 2021). "Findings from a phase I clinical trial indicate that the EZH2 inhibitor is effective against multiple types of hematological malignancies and advanced solid tumors, and phase II studies with the EZH2 inhibitors are ongoing." (PMID 31410199, 2019). "This review summarizes the roles of EZH2 in normal and pathologic hematological processes and recent advances in the development of EZH2 inhibitors for the personalized treatment of patients with hematological malignancies." (PMID 26497210, 2016). "In 1996, EZH2 was first discovered as a binding partner of Vav oncoprotein in hematological malignancies." (PMID 27239242, 2016). "Notably, actionable or druggable gene mutations in EZH2, SUZ12, or EED are mostly observed in hematologic malignancies." (PMID 39565059, 2024). "However, EZH2 inhibitors have only shown efficacy in certain types of hematologic malignancies, and the clinical advantages of EZH2 inhibitors are still considered inadequate." (PMID 39043634, 2024). "Encouragingly, preclinical assessment of the third-generation epigenetic modifying drugs ivosidenib (an isocitrate dehydrogenase 1 inhibitor) and tazemetostat (an EZH2 inhibitor) show enhanced potency and broader spectrum of cytotoxicity for hematological malignancies and solid cancers." (PMID 36060800, 2022). "EZH2 inactivation was also observed in hematological malignancies." (PMID 36428492, 2022). "In the past decade, numerous epigenetic modifiers have been used for the clinical treatment of patients with hematologic malignancies, including inhibitors of DNA methyltransferases (DNMTs), enhancers of zeste homolog 2 (EZH2), histone deacetylases (HDACs), and isocitrate dehydrogenases (IDHs)." (PMID 35031597, 2022). "EZH2 is a histone methyltransferase associated with transcriptional repression through H3K27me2/3, and EZH2-mediated H3K27 methylation is closely related to pathological processes and poor prognosis in hematological malignancies." (PMID 33743723, 2021). "EZH2 overexpression was found initially in hematological malignancies." (PMID 33072570, 2020). "Experimental modulation of EZH2 expression in a cell-stage specific manner during hematopoiesis might help validating this hypothesis and improving our understanding of EZH2 role in hematological malignancies." (PMID 26497210, 2016). "EZH2 up-regulation has been linked to gene amplification in several solid cancers, but not in hematological malignancies." (PMID 26497210, 2016). "While we did not observe in BTIC lines EZH2 activating point mutations Y641 and A677 that occur in hematological malignancies, an increase in copy number variations (CNV) was detected in the majority of those lines." (PMID 27449082, 2016). "Therefore, a link between c-MYC deregulation and EZH2 overexpression could be involved in the physiopathology of hematological malignancies." (PMID 26497210, 2016).
hematological malignancies (continued). "It is well known that 3-deazaneplanocin A (DZNep), an inhibitor of S-adenosylmethionine-dependent methyltransferase that targets the degradation of EZH2, preferentially induces apoptosis in various hematological malignancies, suggesting that EZH2 may be a new target for epigenetic treatment." (PMID 24492606, 2014). "Clinical trials have shown promising results with EZH2-specific inhibitors, including GSK126, EPZ6438, PF-06821497, Tazemetostat and CPI-1205, in treating hematological malignancies and other tumors." (PMID 37752998, 2023). "Enhancer of zeste homolog 2 (EZH2) and Bruton’s tyrosine kinase (BTK) are both key factors involved in the development and progression of hematological malignancies." (PMID 37752998, 2023). "Tazemetostat, an EZH2 inhibitor, is also being tested in clinical trials for a variety of solid tumors as a single agent or as a combinatorial agent, and it should not be long before clinical trials in hematological malignancies are carried out as well." (PMID 38997742, 2024). "However, inhibitors of EZH2 have not provided clinical benefits and are limited to certain hematological malignancies." (PMID 31367244, 2019).
adenocarcinoma (28 papers, 2011 to 2025). A common cancer characterized by the presence of malignant glandular cells. "Within the adenocarcinoma subtype, higher EZH2 expression was notably associated with younger age, smoking history, and advanced TNM stage." (PMID 37909018, 2023). "EZH2 overexpression associated with poor prognosis in Asian population, adenocarcinoma and stage I patient." (PMID 33681204, 2021). "Adenocarcinoma-specific mRNA expression levels of EZH2 and RRM1 are associated with poor post-surgical survival in the first set of patients, but not replicated in a clinically and pathologically matched independent validation set." (PMID 30458017, 2018). "Applying this MR-TF list to our snRNA-seq data we observed NEPC related MT-TFs were enriched within our DKO vehicle treated (L2) population and EZH2 inhibition generated subpopulations enriched for transitional and adenocarcinoma MR-TFs." (PMID 40832297, 2025). "Collectively, our study demonstrates the control by EZH2 catalytic function in cellular plasticity and the numerous cell state transitions that converge during progression of adenocarcinoma to NEPC." (PMID 40832297, 2025). "Specifically, EZH2 suppressed the initiation of Kras-driven adenocarcinoma but promoted adenocarcinoma progression." (PMID 38036730, 2023). "Because the mouse model we used was adenocarcinoma, and became more poorly differentiated when Ezh2 was deleted, we next focused only on ADCs and poorly differentiated lung tumors." (PMID 36670102, 2023). "Another study, confirmed through immunohistochemistry, established that EZH2 expression exhibited a significant increase in squamous lung carcinoma compared to adenocarcinoma." (PMID 37909018, 2023). "EZH2 and RRM1 mRNA expression in resected stage I adenocarcinoma were associated with survival in a first validation set, but not replicated in a clinically and pathologically matched independent set." (PMID 30458017, 2018). "Our atypical hybrid SCPCs, as well as the outlier adenocarcinoma, overexpressed epigenetic genes including EZH2." (PMID 29132337, 2017). "It has been shown that EZH2 complexes directly with N-Myc in order to transcriptionally repress the genes that enforce an AR-driven adenocarcinoma state in NEPC, and that EZH2 knockdown leads to the de-enrichment of neuronal-associated pathways in NEPC organoids." (PMID 36430730, 2022). "Hormone-naive PDX adenocarcinoma model, LTL331, and castration-resistant NEPC subline, LTL331R, reflect this finding with the upregulation of EZH2 expression in the latter." (PMID 39682746, 2024). "In agreement with their more aggressive behavior adenocarcinomas of composite mice also have higher proliferative rate, increased number of CK5 and p63 positive cells, and elevated levels of EZH2 expression." (PMID 32205838, 2020). "In our previous study in resected NSCLC, we observed that BRCA1 expression was higher in squamous cell than in adenocarcinomas; in addition, in our experience, the expression of BRCA1 and EZH2 was significantly higher in small-cell than in NSCLC." (PMID 21951562, 2011). "Therefore, high EZH2 can indicate lower PRC2 function, and our mouse model and in vitro data show that one result of lowering PRC2 function in KRAS-driven adenocarcinomas is to de-repress FOXP2." (PMID 36670102, 2023). "Importantly, although H3K27me3 was heavily reduced in tumors lacking Ezh2 in 9- to 12-mo-old mice, invasive adenocarcinomas still formed with full penetrance (n = 6)." (PMID 26637281, 2015). "We observe a positive correlation between INPP4B and EZH2 expression in the human prostate epithelium and primary adenocarcinomas and, consistent with previous reports, a negative correlation between PTEN and EZH2." (PMID 38001678, 2023). "Furthermore, the EZH2-mediated regulation of cell cycle genes are lost in NEPC, unlike in adenocarcinoma, suggesting increased cell cycle dysfunction." (PMID 39682746, 2024).
prostate (15 papers, 2015 to 2026). "Above all, our data support YTHDF1 as a critical downstream effector of EZH2 to promote prostate carcinogenesis." (PMID 41252201, 2026). "Here, the demonstration of a critical axis of EZH2-HNF1B/RBBP7-SLUG in prostate cancer development, provides mechanistic insights of EZH2-mediated prostate tumorigenesis and molecular basis for the application of EZH2 inhibitors." (PMID 31636385, 2020). "Therefore, EZH2 inhibition is likely to have a protective impact on CaOx-induced kidney injury." (PMID 38169402, 2024). "Another group demonstrated that G9a is recruited to DNA damage sites with other repressive chromatin proteins such as enhancer of zeste homolog 2 (EZH2) and DNA methyltransferase (DNMT) and maintained transcriptional silencing of tumor suppressor genes in colorectal cancer." (PMID 33468997, 2021).
hematological cancers (13 papers, 2018 to 2026). "Tz is an FDA-approved drug used for long term treatment of hematopoietic cancers with activated EZH2 (ClinicalTrials.gov ID NCT02875548)." (PMID 39703699, 2024). "Recently, the Enhancer of zeste homolog 2 (EZH2) inhibitor tazemetostat received U.S. Food and Drug Administration (FDA) approval for the treatment of patients with solid malignancies and hematologic cancers." (PMID 38723947, 2024). "In non-hematologic cancers, DNA binding of ZNF217 to specific cis-regulatory regions correlates negatively with gene expression, suggesting its function as a transcriptional repressor through interaction with epigenetic regulators such as CoREST, CtBP, LSD1, and EZH2." (PMID 37648814, 2023).
neurological diseases (12 papers, 2015 to 2025). "More efforts may still be paid to evaluate Ezh2-implicated epigenetic regulation of neuronal development and its mutation-related neurological diseases." (PMID 26499080, 2015). "This review aims to explore the contribution of EZH2 activity in neuroinflammation, delineate the underlying destructive or protective mechanisms and present potential targeting options for therapeutic intervention in neurological disorders with inflammatory background." (PMID 40723311, 2025). "EZH2-driven astrocytic changes play a significant and context-dependent role in shaping the clinical course of several neurological diseases." (PMID 40723311, 2025). "Following these studies, it is evident that EZH2 inhibition in neurological diseases can be a promising therapeutic approach with beneficial outcomes for certain conditions, bearing in mind that its effects are highly stage- and context-dependent." (PMID 40723311, 2025). "In the CNS, the physiological activity of EZH2 relies on proper neuronal function maintenance via the downregulation of genes responsible for nervous system disorders." (PMID 40723311, 2025). "Due to its critical involvement, EZH2’s abnormal performance was also a strong indicator of several neurological disorders." (PMID 29156711, 2017). "To date, EZH2 has not been associated with the environmental etiology of the neurological diseases." (PMID 29156711, 2017). "In the last decade, various studies focused on the role of EZH2, an essential component of PRC2, in neurological diseases." (PMID 37391829, 2023).
renal disease (9 papers, 2019 to 2025). "Increasing evidence shows that EZH2 is associated with a variety of kidney diseases and pathology." (PMID 33679454, 2021). "Our study further validated the anti-fibrosis efficacy of EZH2 inhibitors in animal models of renal disease, and provided theoretical support for the use of EZH2 inhibitors in clinical trials." (PMID 37029114, 2023). "The methyltransferase Enhancer of zeste homolog 2 (EZH2) is an important epigenetic regulator and has been intensively studied in the field of renal diseases." (PMID 35439976, 2022). "Key lysine and arginine methyltransferases under investigation for renal disease treatment include EZH2, G9a, DOT1L, PRMT1 and PRMT5." (PMID 35559246, 2022). "In this article, we summarize the role of EZH2 in the pathology of renal injury and relevant mechanisms and highlight EZH2 as a potential therapeutic target for kidney diseases." (PMID 33679454, 2021). "Given that EZH2 plays a protective role in podocytes, EZH2 inhibitors should be avoided in renal diseases characterized by podocyte injury." (PMID 31866860, 2019). "Despite great progress in clinical trials in determining the potential of EZH2 inhibitors as cancer therapy, the efficacy of those inhibitors in animal models of kidney diseases and in human kidney diseases hasn’t yet been shown." (PMID 31866860, 2019). "EZH2 inhibition on kidney diseases in various in vitro and in vivo models." (PMID 33679454, 2021). "We also highlight EZH2 as a potential target for ameliorating fibrosis in kidney disease." (PMID 33679454, 2021). "This article reviews the role of EZH2 in the pathology of renal disease and relevant mechanisms." (PMID 33679454, 2021). "Moreover, pharmacological or genetic inhibition of EZH2 can interfere with pathologic fibrosis in these animal models of kidney disease." (PMID 33679454, 2021). "However, even in the few studies, the role of EZH2 in kidney diseases remains largely controversial." (PMID 32508971, 2020). "Enhancer of zeste homolog 2 (EZH2) is a well-recognized methyltransferase that can mediate H3K27me3 and exert an important role in multiple kidney diseases." (PMID 34462420, 2021). "Emerging evidence has shown increased expression of some HMTs such as EZH2, G9a, SUV39H1, and SET7/9 in several kidney diseases." (PMID 31866860, 2019). "Enhancer of zeste homolog 2 (EZH2), a recently discovered histone methyltransferase, induces trimethylation at lysine 27 of histone H3 (H3K27me3), and plays an important role in renal diseases." (PMID 37029114, 2023). "However, the role of EZH2 in nonneoplastic diseases, such as kidney diseases, is unknown and has been investigated." (PMID 32508971, 2020). "Finally, although clinical trials of some EZH2 and DOT1L inhibitors for treatment of tumors have been reported, there are still no clinical trials for HMT inhibitors in renal diseases." (PMID 31866860, 2019).
cardiovascular diseases (6 papers, 2016 to 2024). "Since the epigenetic enzyme Enhancer of Zeste Homolog 2 (EZH2) and its concomitant mark H3K27Me3 have been shown to be elevated in many cardiovascular diseases that associate with EndMT, we hypothesized that H3K27Me3 is a determinant for the susceptibility of EndMT." (PMID 38774662, 2024). "Previous studies, including our recent work, have shown that Neat1 can directly interact with Ezh2 to regulate cardiovascular diseases." (PMID 38646788, 2024).